CD38 (CD38 molecule)
Diseases named in the same sentence as CD38 in open-access papers (continued):
Sharing a sentence is not in itself a finding about the gene and the disease.
tumor (continued). "In conclusion, this investigation elucidated a new CD38-mediated mechanism of immune evasion in ICI-treated patients based on the paracrine exchange in the TME of extracellular adenosine between tumor cells and immune cells." (PMID 36078044, 2022). "This biologic can be manufactured at large scale and can be used to target CD19, CD38, or other specific tumor targets using the corresponding CAR-T cell design." (PMID 35203590, 2022). "Seven days after tumor injection, mice received CD38-CAR-T cells, a single dose of 8 × 106 CD38-CAR T cells, and non-transduced T cells." (PMID 35765110, 2022). "Ex vivo flow cytometric analyses of CD38-positive tumors was performed six hours post-injection to quantify the relative amount of in vivo injected and still tumor-bound JK36AF680." (PMID 36389758, 2022). "The presence of CD38 in CLL is associated with a worse survival prognosis, as well as an increase of CD38 expression on tumor cells, which reflects a switch to a more aggressive CLL type." (PMID 36611312, 2022). "Strategies targeting the CD38-NAD axis can improve the efficacy of anti-tumor adoptive T cell therapy." (PMID 35906622, 2022). "CD38 appears to be robustly detected in the lymphocytic infiltrate from the tumor microenvironment of classical Hodgkin lymphoma, reminiscent of powerful immunosuppressive roles it mediates in the bone marrow niche of MM." (PMID 36139103, 2022). "Addition of fluorescein-conjugated anti-EGFR monoclonal antibody resulted in cell lysis of EGFR-expressing tumor cells while addition of fluorescein-conjugated anti-CD38 monoclonal antibody resulted in cell lysis of CD38-expressing tumor cells." (PMID 36531912, 2022). "Multiple B-cell subpopulation markers are unevenly expressed in B cells, such as CD22, CD27, and CD38, suggesting B-cell heterogeneity in the tumor microenvironment." (PMID 35634306, 2022). "Consistently, our in vivo results showed that inhibition of the enzymatic activity or antagonizing the enzymatic product of CD38 resulted in the similar inhibition of tumor proliferation and metastasis as CD38 gene knock-out or mutation." (PMID 34226519, 2021). "These preclinical data were confirmed in human specimens of lung and melanoma cancers showing a tight relationship between CD38 expression and a cytolytic T cell tumor infiltrate." (PMID 33418913, 2021). "Real-time fluorescence monitoring experiments, luciferase detection experiments and flow cytometry experiments revealed the efficient and specific killing abilities of CD38 CAR-T cells against CD38-positive tumor cells." (PMID 34513682, 2021). "More recently, Chen L uncovered a novel mechanism that tumor expressed CD38 was upregulated in tumor-bearing mice that responding to PD-L1 antibody, which led to immune tolerance and resistance." (PMID 34226519, 2021). "Members of families 2, 4 and 5 effectively induce complement-dependent cytotoxicity against CD38-expressing tumor cell lines, while all families effectively induce antibody dependent cellular cytotoxicity." (PMID 34539634, 2021). "Our results also found the risk score based on a 5-mRNA signature was significantly associated with tumor mutational burden (TMB) and tumor stem cell markers (CD20, CD38, ABCB5, CD44, etc.)." (PMID 34805163, 2021). "Mice bearing CD38+ RPMI 8226 tumours were i.v. injected with either 111In-DPTA-2F8 alone, 111In-DPTA-2F8 in combination with 150 mg/kg gelofusin or 111In-DTPA-R3B23." (PMID 34727950, 2021). "More importantly, in EAC and ESCC, high expression of CD38-positive MDSCs is abundantly found in the peripheral blood at advanced stage, while Daratumumab binding with CD38 expression reduces tumor growth." (PMID 34434889, 2021). "CD38 KO and MU tumor cells showed a higher expression of KEAP1 than that of WT and OE cells, while NRF2 was on the contrary." (PMID 34226519, 2021). "Future research is needed to unravel the role of CD38 in tumor promotion and immunomodulatory effect." (PMID 34211854, 2021).
tumor (continued). "All the results demonstrated the specificity and activity of BM38 CAR-Ts against BCMA+ or CD38+ tumor cells." (PMID 34627333, 2021). "The CD38-CAR T-cells specifically and efficiently lysed CD38+ MM cell lines and inhibited tumor growth in NOD/SCID mice." (PMID 34575943, 2021). "Treatment with the anti-CD38 antibody in mice that are resistant to IC blockade therapy inhibits tumor growth, enhances effector CD8+ and CD4+ T-cell responses and reduces CD4+ Treg cells and MDSCs." (PMID 33467713, 2021). "Another study reported CD38 expression within the TME including tumour and certain immune subsets, such as macrophages as a predictive marker of responsiveness to anti-PD-1/PD-L1 single agent treatment in HCC patients." (PMID 34104078, 2021). "Studies of the role of CD38 in the progression of oncogenesis and mechanisms of tumor evasion from immunity are ongoing." (PMID 34685490, 2021). "CD38 was well known as a major NAD glycohydrolase and participated in the generation of adenosine (ADO) and our results showed that the enzymatic activity of CD38 was important for tumor progression." (PMID 34226519, 2021). "Again, indicating that RP02 CAR‐T cells, while cytotoxic for CD38‐expressing tumor cells, show very little activity toward cells expressing the low levels of CD38 that would be found in normal tissue." (PMID 33747727, 2021). "The CD38 antibodies also improve host-anti-tumor immunity by elimination of regulatory T-cells, regulatory B-cells, and MDSCs." (PMID 33922005, 2021). "Daratumumab (IgG1 monoclonal antibody) binds to CD38; the Fc component of daratumumab binds to FcγRs on the macrophages and then phagocytosis of opsonized tumor cells." (PMID 34141513, 2021). "CD38 negative or low NK cells are resistant to daratumumab-induced fratricide and have improved tumor cytotoxicity when combined with daratumumab compared to CD38+ NK cells." (PMID 33766099, 2021). "Although the binding of RP02 antibody to CD38 is weaker than that of 028 antibody, when activated by CD38‐positive tumor cell lines, RP02 CAR‐T cells consistently produced a stronger cytokine response than 028 CAR‐T cells." (PMID 33747727, 2021). "As daratumumab is a monoclonal antibody to CD38, these cells are sensitive to daratumumab and hence promote anti-tumor activity." (PMID 34141513, 2021). "Considering the important role of CD38 in immune cells, we also assessed the relationship between CD38 and peripheral blood lymphocyte subsets as well as tumor infiltrating immune cells." (PMID 34211854, 2021). "The knockout of CD38 inhibited anchorage-independent cell growth, cell invasion, and significant reduction of tumor growth." (PMID 34211854, 2021). "Several studies have shown the importance of CD38 as a factor contributing to tumor development due to a change in the local metabolic microenvironment of the tumor from pro-inflammatory to anti-inflammatory, including the polarization of macrophages." (PMID 34685490, 2021). "Expression of CD38 was found in 15–23% of cancer incidents with a strong correlation to the inflammatory mechanism in the tumour microenvironment." (PMID 34572431, 2021). "Then, we collected samples from 51 NSCLC patients to study the biological feature and response to anti-PD-1 of tumor-infiltrating CD38+ CD8+ T cells in vitro." (PMID 33934206, 2021). "Baseline tumor CD38 expression levels were evaluated by immunochemistry in 22 patients (responders, n = 6; nonresponders, n = 16)." (PMID 33588922, 2021). "The results of bioluminescence imaging in vivo showed that compared with the control group or Pan-T group, the tumor of the CD38 CAR-T cell groups was cleared completely after the second injection of CD38 CAR-T cells." (PMID 34513682, 2021). "Reduction of CD38 expression in spleens modulated by the cascaded double-target biomimetic nanosystem-based PTT was relatively smaller than that in tumor tissues, so did the myeloid and lymphoid." (PMID 34930285, 2021).
tumor (continued). "Compared with normal lung samples, both PD-1+ and CD38+ CD8+ T cells were significantly enriched in tumor samples." (PMID 33747957, 2021). "One recently reported mechanism of resistance to PD-1 antibodies in other tumor types is through the upregulation of CD38." (PMID 34070758, 2021). "A functional relationship between the subset of Th17 immunosuppressive TILs and Cd38+ expressing cells has also been described, and the targeting of subpopulations with high CD38 expression can also restore tumor control via adoptive cell therapy (ACT)." (PMID 33384409, 2021). "Taken together, these observations suggest that increased CD38 expression is directly related to anti-tumor immune response suppression and/or inhibition of migration." (PMID 33936090, 2021). "Understanding the essential mechanisms of CD38 employed by tumor cells in tumor microenvironment represents an attractive therapeutic opportunity to selectively target tumor cells." (PMID 34226519, 2021). "In this study, we aimed to develop anti-CD38 single-domain antibodies (sdAbs) that can be used to trace CD38+ tumour cells and subsequently used for targeted radionuclide therapy." (PMID 34727950, 2021). "By RNA-Seq, CD38 was highly expressed by LLC1 tumor cells and, therefore, anti-CD38 antibody treatment was combined with L82-pulsed DC vaccination." (PMID 34771674, 2021). "This conclusion was reinforced by additional studies were T cells were treated with TGF-β (which mimics tumor immune suppression) and then with anti-CD38 antibody." (PMID 33936090, 2021). "This is in line with the findings of others that extracellular NAD+ accumulation owing to CD38 blockade decreased Tregs in the tumor." (PMID 34771674, 2021). "Tumor associated microglia/macrophages (TMM), formed by a small proportion of resident brain CD38+ microglia and infiltrating monocytes, constitute 40% of the tumor." (PMID 33727923, 2021). "The role of CD38 in tumor-mediated inhibition of T cell functions has been extensively studied in the multiple myeloma (MM) model, where malignant plasma cells (PC) grow in a hypoxic bone marrow (BM) niche." (PMID 33936090, 2021). "By eradicating CD38-expressing MDSCs, Tregs and Bregs, daratumumab potentially restores anti-tumor immune responses with an increase in NK and T cells expansion, activation and clonality." (PMID 33799565, 2021). "In immunocompetent mouse, we found that CD38 MU and KO tumor cells exhibited the impaired capability of tumor growth, mass and lung metastasis compared with CD38 WT and OE group." (PMID 34226519, 2021). "We determined the lytic capacity of RP02 and RP03 CAR‐T cells versus two CD38‐positive tumor cell lines (Daudi and RPMI‐8226)." (PMID 33747727, 2021). "CD38-targeting antibodies have immunomodulatory effects such as improving the host-anti-tumor immune response." (PMID 34093594, 2021). "Approximately 96% of these tumor cells co-expressed cytoplasmic kappa and lambda light chain based on a CD38-positive gate strategy." (PMID 34930458, 2021). "ICI therapy can also upregulate cluster of differentiation 38 (CD38) on tumor cells, leading to immune suppression and resistance to therapy." (PMID 33467713, 2021). "The chance to treat HPD patients with CD38 inhibitors is a real opportunity to overcome tumor acceleration." (PMID 33467713, 2021). "Next, we compared the degree of activation of tumor-infiltrating PD-1+ CD3+ CD+ T cells with tumor-infiltrating PD-1+ CD38− CD+ T cells using CD69 and HLA-DR, which are the markers of T cell activation." (PMID 33934206, 2021). "Our hcAbs present unique tools to assess cytotoxicity mechanisms of CD38-specific hcAbs in vivo against tumor cells and potential off-target effects on normal cells expressing CD38 in syngeneic mouse tumor models, i.e. in a fully immunocompetent background." (PMID 34539634, 2021). "It has been proposed that the enzymatic activity of CD38 contributes to a microenvironment favourable for tumor survival in the bone marrow niche." (PMID 34539634, 2021).
tumor (continued). "Collectively, our data showed that the enzymatic activity of CD38 was required for tumor progression." (PMID 34226519, 2021). "Lastly, an anti-CD38 mAb was radiolabelled with the alpha-particle emitting radionuclide Astatine-211 (211At), which also showed to delay tumour growth in MM models with subcutaneous tumours or with minimal residual disease." (PMID 34727950, 2021). "CD38, primarily a NAD + glycohydrolase and ADPR cyclase, is a multifunctional transmembrane protein whose abnormal overexpression in a variety of tumor types is associated with cancer progression." (PMID 33727923, 2021). "Herein we reported that tumor expressing CD38 promoted tumor cell progression via its enzymatic product cADPR independent on NAD+ homeostasis and the production of adenosine." (PMID 34226519, 2021). "Of interest, a very recent study demonstrated that resistance against CD38-targeting mAbs is, at least in part, related to microenvironment-mediated downregulation of CD38 on tumor cells." (PMID 34680303, 2021). "CD38 has come into consideration as its involvement in adenosine-mediated immunosuppression within the tumor microenvironment has been established." (PMID 33727923, 2021). "The results showed that the expression of CD38 in HNSCC was positively correlated with tumor infiltrating lymphocytes, indicating that CD38 exerted anti-tumor or pro-tumor effects depending on microenvironment property." (PMID 34211854, 2021). "They showed that ATRA increased the CD38 expression on AML cells, and subsequently, remarkable cytotoxicity of CD38-CAR T cell combined with ATRA was observed in eliminating the tumor cells." (PMID 34412685, 2021). "It is interesting that tumor-infiltrating CD38+ CD8+ T cells are more efficient to be reinvigorated by anti-PD-1 than CD38− CD8+ T cells in vitro." (PMID 33934206, 2021). "The selective inhibition of CD38 with a monoclonal FDA-approved antibody called daratumumab (DARA) enhances tumour immune recognition and reduces tumour growth in vitro and in GBM mouse models." (PMID 33804731, 2021). "We used immunophenotyping by multiparameter flow cytometry to examine the effects of APVO436 on tumor burden reflected by CD123+CD34+CD38- target blast cells." (PMID 35096610, 2021). "By means of CD38/Egr2 classification, we observed that, in all tumor types, the proportion of M2 TAMs declined after IT, while that of M1 TAMs increased in TC-1- and TC-1/A9-treated tumors." (PMID 34205330, 2021). "It is interesting that CD38+ CD8+ T cells in tumor had a stronger secretion of IFN-γ than CD38− CD8+ T cells, but not in normal tissues and peripheral blood." (PMID 33934206, 2021). "Of note, IL6, IGFBP3, and CXCL16 were identified as the tumor-derived factors responsible for the induction of CD38 expression in MSDC ex vivo." (PMID 33390169, 2021). "At the transcriptional level, CD38 in tumor was positively correlated with infiltrated T cell exhaustion." (PMID 34211854, 2021). "Panobinostat combined with the anti-CD38 monoclonal antibody danatuximab augments CD38 expression and enhances danatuximab monotherapy with significant anti-tumor activity in MM." (PMID 34001246, 2021). "Accordingly, tumor-bearing mice undergoing adoptive transfer of T cells after anti-CD38 treatment had longer survival times and better control of tumor growth than mice treated with anti-CD38 or T cells alone." (PMID 33936090, 2021). "Along with inhibition of TRPM2 by siRNA or 2-APB, the decreasing concentration of calcium was observed in CD38 WT and OE tumor cell than that of control." (PMID 34226519, 2021). "It has been proposed that CD38 contributes to shaping an immunosuppressive tumor microenvironment (TME) by fuelling the conversion of NAD+ to immunosuppressive adenosine." (PMID 34539634, 2021). "At the other end, daratumumab (and isatuximab) targets CD38 on the population of normal and tumor plasma cells, in this way reducing vaccines immunogenicity by direct depletion of antibody producer cells." (PMID 34001183, 2021).
tumor (continued). "CD38 expression and its role in the inhibition of anti-tumor immune response has been described in solid and hematological tumors." (PMID 33936090, 2021). "The 68Ga-anti-CD38 nanobody demonstrated rapid accumulation in tumors (1.76 ± 0.305%ID/g (n = 5)) 1 h post-injection, which was accompanied by a promising tumor-to-bone ratio (TBR = 5.79) as well as evidence of rapid renal clearance." (PMID 33925941, 2021). "Here we uncovered the correlation between CD38 expression and survival and immune infiltration levels in tumor of NSCLC." (PMID 33934206, 2021). "We found that the TNF-α secretion in tumor-infiltrating CD38− CD8+ T cells was significantly decreased when compare with CD38− CD8+ T cells in paired normal tissues, but not in tumor-infiltrating CD38+ CD8+ T cells." (PMID 33934206, 2021). "Unsupervised clustering further identified a group of AICDA+ and MKI67+ proliferative B cells and CD38+ plasma cells in tumor samples, underscoring the existence of functionally active GCs." (PMID 34164398, 2021). "Despite high activation, the majority of tumor infiltrating CD8 T cells in protein vaccine treated mice expressed PD-1, Tim-3, CD38, and NKG2a markers associated with T cell exhaustion." (PMID 34276686, 2021). "Using CD38 as the target antigen, an efficient and effective selection of CARs specifically recognizing CD38+ tumor cells is demonstrated." (PMID 33747727, 2021). "CD38 belongs to the ribosyl cyclase family and is expressed on various hematological cells and involved in immunosuppression and tumor promotion." (PMID 34211854, 2021). "Despite the data obtained, it is clear that further studies are required into the expression and activity of CD38 in cells of the tumor microenvironment with a pronounced regulatory potential." (PMID 34685490, 2021). "We also discovered that CD38 expression positively correlated with PD-1, CTLA-4, TIGHIT, GITR, LAG-3, and VISTA, indicating that upregulated CD38 levels in tumor microenvironment mediated ICI-resistance." (PMID 34211854, 2021). "We further illustrated that CD38 was certainly expressed on multiple tumor cell lines across human and murine species." (PMID 34226519, 2021). "Our aim was to select antibodies capable of discriminating between tumor cells with a high level of CD38 expression and normal healthy cells with a low level of CD38 expression." (PMID 33747727, 2021). "CD38 expression is increased during inflammation and tumor transformation, and is paralleled by CD73 up-regulation." (PMID 33936090, 2021). "Lastly, recent data indicate that CD38 is highly expressed by specific subsets of immunosuppressive tumor infiltrating lymphocytes, including regulatory T cells and T helper 17 cells." (PMID 34421911, 2021). "By adding cADPR and 8-Br-cADPR to co-culture tumor cells, we found that cADPR inhibited the expression of KEAP1, but promoted the expression of NRF2 in CD38 KO and MU tumor cells, while 8-Br-cADPR was on the contrary." (PMID 34226519, 2021). "While CD38 expression on B cells remains the main theme of current research, more data is beginning to be gathered concerning the role of CD38 expression on tumor cells." (PMID 33629216, 2021). "The knockout of CD38 on tumor cells reduced the invasion and progression of tumors in nude mice models, while the expression of CD38 by tumor cells enhanced in vitro and in vivo growth." (PMID 33467713, 2021). "Despite the cooperation of CD38 in effector cytotoxic responses, the enzyme is involved in immune escape and tumor growth." (PMID 33467713, 2021). "There was no significant increase in total CD8+ T cells, but both PD1+ and CD38+ CD8+ T cells were significantly enriched in tumor samples and statistically significantly associated with tumor size." (PMID 33747957, 2021). "CD38 ubiquitously presented in tumor cells (TCs), fibroblast-like cells (FLCs), and tumor-infiltrating lymphocytes (TILs)." (PMID 34211854, 2021).